PTX3 (pentraxin 3)
Diseases named in the same sentence as PTX3 in open-access papers (continued):
Sharing a sentence is not in itself a finding about the gene and the disease.
Stroke (continued). "This loss of BBB tightness associated with PTX3 downregulation was due at least in part to the dysregulation of tight junction accessory proteins, suggested by a decrease in ZO‐1 expression after stroke in mice that received PTX3 siRNA." (PMID 33314664, 2021). "In summary, this study demonstrates that PTX3 is an important NVU mediator for stroke pathology in white matter by showing the biphasic roles of PTX3 after white matter stroke—beneficial during the acute phase, but detrimental during the chronic phase." (PMID 33314664, 2021). "Our reverse translational study reveals the biphasic roles of PTX3 after white matter stroke and provides a proof‐of‐concept that PTX3 can be a therapeutic target for stroke." (PMID 33314664, 2021). "Because white matter damage is a clinically important aspect of cerebrovascular diseases, we used mouse models of white matter stroke in a reverse translational study to examine the roles of PTX3 in stroke pathology, focusing on cerebrovascular function." (PMID 33314664, 2021). "Western blotting using corpus callosum samples from stroke mice showed that the increased expression of PTX3 was sustained until at least day 21 after injury." (PMID 33314664, 2021). "Compared to mice that received control siRNA injection at day 7, mice that received PTX3 siRNA injection at day 7 showed larger numbers of BrdU/CD31‐double positive cells (newly emerged endothelial cells) at day 21 after stroke onset." (PMID 33314664, 2021). "In contrast to that of experimental evidence from animal studies, PTX3 has been shown to positively correlated with stroke severity and provides an indication for poor prognosis and prediction of mortality after ischemic stroke." (PMID 33210471, 2021). "Our current findings support the idea that PTX3 would be an attractive therapeutic target for white matter‐related disease, including stroke." (PMID 33314664, 2021). "Significant increases in stroke patients versus controls were obtained for serum PTX3 (3.14 ± 1.23 vs. 2.44 ± 0.74 ng/ml; p < .001) and C‐reactive protein (CRP – 1.53 ± 0.38 vs. 1.35 ± 0.35 μg/ml; p < .05)." (PMID 33210471, 2021). "We first examined PTX3 expression levels in cerebral white matter after stroke in human and mouse samples." (PMID 33314664, 2021). "As a key regulator of angiogenesis, PTX3 is emerging as a promising target for cerebrovascular repair after stroke." (PMID 33210471, 2021). "In cerebrovascular diseases, PTX3 represents baseline atherosclerotic burden more accurately in acute stroke and is related to the severity of the stroke." (PMID 31998222, 2019). "Collectively, these data suggest that long-term CBF recovery after cerebral ischaemia is impaired in PTX3 KO mice, suggesting a key role for PTX3 in long-term restoration of blood flow post-stroke." (PMID 30315331, 2018). "Pentraxin 3 (PTX3) is a key regulator of angiogenesis and is emerging as a promising target for cerebrovascular repair after stroke." (PMID 30315331, 2018). "The aim of this study was to characterize the role of PTX3 in post-stroke neurogenesis, angiogenesis and functional recovery." (PMID 25616391, 2015). "The acute phase protein pentraxin 3 (PTX3) is a new biomarker of stroke severity and is a key regulator of oedema resolution and glial responses after cerebral ischaemia, emerging as a possible target for brain repair after stroke." (PMID 25616391, 2015). "Here, we investigated for the first time the role of PTX3 in neurogenesis and angiogenesis after stroke." (PMID 25616391, 2015). "Here we show for the first time that the acute phase protein PTX3, a biomarker of stroke severity, is a key regulator of neurogenesis and angiogenesis after cerebral ischaemia, and that it has an impact on the recovery of motor function." (PMID 25616391, 2015).
Stroke (continued). "PTX3 has been shown to participate in other post stroke responses such as resolution of oedema and glial scar formation; here we observe that, 6 days after the ischaemic event, PTX3 promotes repair in the form of neurogenesis, especially in the hippocampus." (PMID 25616391, 2015). "For the composite endpoint, the p-value for interaction in the multivariable analysis demonstrates a significant sex difference in the prognostic weighting of PTX3 (p = 0.027), suggesting that PTX3 acts independently as a predictor in males with respect to total death or MI or stroke." (PMID 39897419, 2025). "Our findings suggest that PTX–3 serves as a novel and reliable predictor for stroke outcome." (PMID 40542581, 2025). "Furthermore, previous studies have shown that PTX3 and miR-21-5p can reduce inflammation, including in models of brain injury and stroke." (PMID 35656007, 2022). "Finally, although our current study showed that PTX3 downregulation by PTX3 siRNA promoted compensatory angiogenesis, a previous study reported that PTX3 ko mice exhibited less angiogenesis after stroke." (PMID 33314664, 2021). "Although serum PTX3 levels were equally increased in all stroke subtypes, the clinical significance of such increases may be quite different among these subgroups." (PMID 33210471, 2021). "Additionally, a deeper understanding of PTX3 roles would help to elucidate the complex mechanisms of stroke pathology." (PMID 33314664, 2021). "Recently, we proposed that pentraxin 3 (PTX3) may be an important NVU mediator that regulates stroke pathology in gray matter." (PMID 33314664, 2021). "Similarly, in a mouse model of white matter stroke (ET‐1 injection into corpus callosum), PTX3 expression was increased in the corpus callosum at day 3 after stroke." (PMID 33314664, 2021). "Therefore, the different cell types, including pericytes and astrocytes, that contribute to PTX3 production under diseased conditions should be tested at multiple time points in disease models other than stroke." (PMID 33314664, 2021). "Despite this, our recent study found that PTX3 mediates delayed neuroprotection after stroke, which is also supported by a previous study demonstrating that PTX3 KO mice have greater neuronal damage than WT mice in an N-methyl-D-aspartate-based epileptic seizure model." (PMID 31602423, 2019). "In this condition, levels of IL-1β in the spleen were also significantly increased after MCAo in PTX3 KO mice, raising the possibility that in stroke neutrophil infiltration regulated by PTX3 could involve IL-1β." (PMID 31602423, 2019). "We have previously shown that brain PTX3 expression is upregulated after experimental stroke in the ipsilateral (stroke) hemisphere in mice, promoting recovery in the brain by reducing oedema and improving blood-brain barrier (BBB) integrity by enhancing glial scar formation." (PMID 30315331, 2018). "Despite these findings, the effect of PTX3 on CBF is currently completely unknown, and the mechanisms underlying PTX3 regulation of post-stroke angiogenesis remain incompletely understood." (PMID 30315331, 2018). "WT and PTX3 KO mice have significantly increased vessel proliferation 48 h, 7 days, 14 days, and 28 days after experimental stroke, indicated by a significantly higher number of KI-67+ vessels and number of KI-67+ vessels as a % of total number of vessels present." (PMID 30315331, 2018). "Impaired CBF in PTX3 KO mice observed in our study led us to hypothesise that PTX3 regulates vessel diameter after experimental stroke." (PMID 30315331, 2018). "Consequently, these results demonstrate for the first time another potential post-stroke pro-angiogenic mechanism driven by PTX3 involving reactive astrocytes." (PMID 30315331, 2018). "Considering these previous findings and our data in this study suggesting that PTX3 promotes expression of GFAP+ astrocytes, we assessed whether PTX3 influences neuronal viability after experimental stroke." (PMID 30315331, 2018).
Stroke (continued). "Published data from our group suggests that PTX3 promotes angiogenesis 14 days after experimental stroke, demonstrated by a decrease in vasculature, fewer newly formed blood vessels, and reduced expression of vascular endothelial growth factor receptor 2 (VEGFR2) in PTX3 KO mice." (PMID 30315331, 2018). "Since neurogenesis is coupled with angiogenesis in the injured brain, we tested whether PTX3 also promotes angiogenesis after experimental stroke." (PMID 25616391, 2015). "This could be due to a decrease in glial proliferation in PTX3 KO mice which has been reported after stroke." (PMID 25616391, 2015). "However, the effects of PTX3 on cerebrovascular function in the neurovascular unit (NVU) after stroke are mostly unknown, and the basic research regarding the roles of PTX3 in NVU function is still limited." (PMID 33314664, 2021). "Finally, we show that PTX3 promotes long-term neuronal viability after experimental stroke." (PMID 30315331, 2018). "However, lack of PTX3 significantly reduced long-term vessel-associated cellular proliferation compared to WT mice in the ipsilateral hemisphere (14 and 28 days post-stroke)." (PMID 30315331, 2018). "Collectively, these findings suggest that PTX3 may enhance long-term post-stroke angiogenesis." (PMID 30315331, 2018). "Importantly, our recent study found that PTX3 is highly expressed in the brain after experimental cerebral ischaemia and that its central expression is critically regulated by the cytokine interleukin-1 (IL-1), a pivotal regulator of inflammation after stroke." (PMID 25616391, 2015). "Importantly, the involvement of PTX3 in cerebrovascular disease such as ischaemic stroke is emerging; peripheral PTX3 levels are strongly increased after experimental stroke in mice whilst plasma PTX3 levels correlate with mortality after ischaemic stroke in human." (PMID 25616391, 2015). "Pan-reactive astrocyte genes (Cxcl10 and Osmr), A1 neurotoxic genes (Amigo2, Ugt1a, Gpc4, H2-D1, and Iigp1), and A2 neuroprotective genes (Ptx3, Thbs2, and Tm4sf1) were all upregulated by NPD1 + RvD1 in the ipsilesional penumbra at 24 h after stroke." (PMID 37270727, 2023). "Our findings lead to the proposal that PTX3, expressed by GFAP‐positive astrocytes, plays an important role as an NVU mediator that regulates stroke pathology through its biphasic effects after white matter stroke." (PMID 33314664, 2021). "For example, during the acute phase of stroke, some soluble factors, such as tissue inhibitor of metalloproteinase 1 (TIMP-1) and pentraxin 3 (PTX3), are secreted in and/or near the damaged area to ease the breakdown of the BBB." (PMID 33260683, 2020). "At least one mechanism likely involves IL-1β upregulation of pentraxin 3 (PTX3), a marker of stroke." (PMID 31293586, 2019). "In contrast, mice expressing PTX3 showed a marked increase in CBF at 14 days and significantly increased CBF 28 days after stroke, when compared to CBF levels at 72 h." (PMID 30315331, 2018). "Crucially, we demonstrate a long-lasting pro-angiogenic effect of PTX3, revealed by a reduction in vessel diameter, proliferation of vessels, cerebrovasculature, and VEGFR2 expression, in PTX3 KO mice compared to wild-type (WT) mice, 28 days after stroke." (PMID 30315331, 2018). "PTX3 also upregulates vascular integrin-β1 expression in the stroke region of WT mice, but not in PTX3 KO mice." (PMID 30315331, 2018). "Vessel diameter was significantly increased after stroke both in the penumbra (42%) and core (28%) region in WT mice, but not in PTX3 KO mice." (PMID 30315331, 2018). "Whilst we found that PTX3 has no direct role in stroke pathogenesis, we found that PTX3 is a key regulator of early repair processes after stroke, including blood brain barrier (BBB) integrity, resolution of oedema and glial scar formation." (PMID 25616391, 2015).
Stroke (continued). "Notably, mice with the PTX3 siRNA injection exhibited more IgG leakage, suggesting that endogenous PTX3 may support BBB tightness in the acute phase of stroke." (PMID 33314664, 2021). "Therefore, we investigated whether PTX3 affects GFAP+ astrocytes and/or Iba1+ microglia 28 days after experimental stroke." (PMID 30315331, 2018). "Furthermore PTX3 may reflect the baseline atherosclerotic burden more accurately than CRP particularly under acute stress conditions, such as stroke, because of differences in amino acid sequences and molecular structures." (PMID 24936646, 2014).
melanoma (24 papers, 2017 to 2025). A malignant, usually aggressive tumor composed of atypical, neoplastic melanocytes. "However, apart from its effects on FGF signaling, autocrine PTX3 in melanoma has been linked to the TLR4/NF-κB signaling pathway, where it exerts opposing effects." (PMID 41479916, 2025). "PTX3 inhibits FGF/FGFR-driven EMT in melanoma cells, repressing the tumorigenic and metastatic potential of melanoma cells." (PMID 41479916, 2025). "In melanoma, PTX3 has been shown to inhibit FGF2-dependent EMT, thereby reducing cell proliferation, carcinogenesis, and metastasis." (PMID 41479916, 2025). "PTX3 overexpression suppresses the proliferation and migration of melanoma cells through FGF trapping approach." (PMID 41479916, 2025). "On one hand, PTX3 has been shown to inhibit angiogenesis and tumorigenesis in cancers such as breast, prostate, colorectal, esophageal, gastric, cervical, and melanoma." (PMID 41479916, 2025). "Under these conditions, PTX3 secreted by melanoma cells promotes tumor migration, invasion, and the expression of EMT factors." (PMID 41479916, 2025). "In melanoma cells, PTX3 production was found to stimulate the expression of EMT-related factors, such as TWIST1, further supporting its role in promoting tumor metastasis." (PMID 39594709, 2024). "In experiments involving melanoma cells, PTX3 was found to interact with inflammatory signaling pathways, such as the TLR4 and NF-κB pathways." (PMID 39594709, 2024). "The overexpression of PTX3 causes melanoma cells to return to their epithelial form, which would suggest that low levels of PTX3 are an unfavorable prognostic factor in melanoma." (PMID 39201656, 2024). "Tumour-derived inflammatory glycoprotein PTX3 promotes melanoma cell invasion through a TLR4-dependent pathway." (PMID 38052785, 2023). "Cancer cell-derived long pentraxin 3 promoted melanoma migration through TLR4/NF-κB signalling pathway." (PMID 35280672, 2022). "Conversely, knockdown of PTX3 significantly decreased the metastatic potential of cervical cancer cells as well as the migration and invasion ability of invasive melanoma cells in vitro." (PMID 34202354, 2021). "Cancer cell-derived long pentraxin 3 enhances melanoma migration and invasion through TLR4/NF-κB signaling pathway." (PMID 34552063, 2021). "Therefore, the role of PTX3 in melanoma remains ambiguous, influenced by the different signaling pathways it engages." (PMID 41479916, 2025). "Melanoma-derived PTX3 promotes cancer cell invasion and migration via TLR4/NF-κB signaling pathway." (PMID 41479916, 2025). "Consistently, we have demonstrated that dedifferentiated melanoma cells express inflammation-related genes such as pentraxin 3 (PTX3), which contribute to melanoma invasiveness and the mesenchymal-resistant phenotype via a Toll-like receptor 4 (TLR4)-NF-κB-TWIST pathway." (PMID 32466585, 2020). "In 2019, it was reconfirmed that PTX3, as a natural FGF trap inhibitor, could significantly suppress melanoma tumor growth and liver metastasis, thus inhibiting the proliferation and migration of melanoma cells, making PTX3 a promising therapeutic target for melanoma patients." (PMID 41479916, 2025). "Among the critical regulons in neoplastic cells with high PTX3 expression, NFKB2 was recently found to mediate melanoma progression." (PMID 35855654, 2022). "PTX3 has been seen to prevent epithelial-mesenchymal changes induced by FGF-2 in human and mouse melanoma cells andalso to prevent metastatic potential by inhibiting FGF-2-mediated cell proliferation and angiogenesis." (PMID 34048179, 2021). "Previous studies have shown that multiple genes in melanoma cells, such as Wnt5a, MELK, and PTX3, can trigger the NFκB signaling pathway, thereby migrating and invading melanoma." (PMID 33679872, 2020). "The anti-angiogenic/anti-tumor potential of PTX3 has been demonstrated in different types of FGF-dependent tumors, including melanoma, prostate and lung cancer." (PMID 30443492, 2018).
melanoma (continued). "For example, PTX3 prevents fibroblast growth factor (FGF)-driven EMT to reduce the motility and invasive capacity of melanoma cells." (PMID 28489600, 2017). "PTX3, a key factor in a subtype of invasive melanoma, can mediate the expression of the EMT transcription factor TWIST1 through a TLR4/MYD88/IKK/NF-κB signaling pathway and drive melanoma cell migration." (PMID 37277447, 2023). "Furthermore, several vascular regulators reduced in SHP2-silenced mouse B16F10 cells and tumors were expressed at significantly higher levels in metastatic compared with primary human melanomas, including ANGPT1, THSB2 (codes for thrombospondin 2), PTX3, FGF7 (also known as KGF), and VEGFA." (PMID 40131370, 2025).